S100A14 (S100 calcium binding protein A14)
Description:
Depending on the context, it can promote cell proliferation or apoptosis. Does not bind calcium.
Synonyms: S100A15; BCMP84
Tractability: Antibody: the Human Protein Atlas places it where antibodies can reach. PROTAC: ubiquitination databases record sites on it; its protein half-life has been measured.
Gene: Protein-coding gene on chromosome 1 (153,614,255 to 153,616,996, reverse strand). Ensembl gene ENSG00000189334.
Subcellular location: Cytoplasm
Subcellular location (Human Protein Atlas): Cell Junctions; Cytosol; Nuclear bodies; Plasma membrane
Gene Ontology:
Molecular function: chemokine receptor binding; protein binding; calcium ion binding; calcium-dependent protein binding
Biological process: defense response to bacterium; positive regulation of granulocyte chemotaxis; positive regulation of monocyte chemotaxis; response to lipopolysaccharide; toll-like receptor 4 signaling pathway; calcium ion homeostasis
Cellular component: cytosol; extracellular exosome; perinuclear region of cytoplasm; cytoplasm
Genetic constraint (gnomAD): Loss-of-function variants: 6 observed, 11.47 expected, observed/expected ratio (o/e) 0.52, 90% interval 0.28 to 1.03. The upper end of that interval is the gene's LOEUF score, 1.03, which puts it in group 4 of 6, group 1 being the genes least tolerant of losing a copy. Missense variants: 121 observed, 135.13 expected, observed/expected ratio (o/e) 0.9, 90% interval 0.77 to 1.04. Synonymous variants: 51 observed, 54.14 expected, observed/expected ratio (o/e) 0.94, 90% interval 0.75 to 1.19.
Homologues: Orthologues: chimpanzee S100A14 (99% identical), pig S100A14 (97% identical), guinea pig S100A14 (94% identical), rabbit S100A14 (93% identical), mouse S100a14 (90% identical), rat S100a14 (90% identical), macaque S100A14 (65% identical), dog S100A14 (60% identical), zebrafish s100s (28% identical), zebrafish s100a10a (25% identical), zebrafish s100t (25% identical), tropical clawed frog s100a11 (21% identical). Paralogues in human: S100A13 (34% identical), S100A9 (27% identical), S100A10 (24% identical), S100A4 (24% identical), S100B (24% identical), S100A1 (23% identical), S100A11 (23% identical), S100A6 (22% identical), S100A12 (21% identical), S100A2 (21% identical), S100A16 (20% identical), SNTN (20% identical), and 9 more.
Diseases named in the same sentence as S100A14 in open-access papers:
S100A14 is named in the same sentence as 51 diseases in open-access papers, as found by Europe PMC text mining. Sharing a sentence is not in itself a finding about the gene and the disease. The quoted sentences say what the papers report.
breast carcinoma (32 papers, 2008 to 2025). "S100A16 expressions, mutually with S100A14, have been linked to a dangerous condition in patients with breast cancer; both proteins, in cooperation, can increase the aggressive activity of breast cancer cells via cytoskeleton functions." (PMID 36613714, 2022). "RNA-Seq, secreted proteomics, ChIP, Western blot, ELISA, transwell assay and neutralizing antibody experiments were employed to investigate the underlying mechanism of S100A14 in breast cancer metastasis." (PMID 32483412, 2020). "Together, these results suggest that the S100A14 copy number is amplified, it is overexpressed, and this overexpression is associated with lymph node metastasis in breast cancer." (PMID 32483412, 2020). "Clinically, S100A14 drives breast cancer metastasis that is associated with an aggressive disease course and poor survival." (PMID 32483412, 2020). "S100A14 was first identified in 2002 by analysing human lung cancer cell lines, and subsequently in 2003 as a membrane-associated protein in breast cancer cells." (PMID 31105881, 2019). "S100A14 was also associated with the capability of breast cancer cells to produce distant metastases and with increased motility and invasiveness of malignant cells in colon cancer cell lines." (PMID 27241529, 2016). "Furthermore, S100A14 associates with the clinical outcome of breast cancer patients as it significantly correlates with lymph node metastasis and reduced OS especially in the luminal B subtype." (PMID 39830522, 2024). "Furthermore, S100A16 coexpression with S100A14 is associated with poor prognosis of breast cancer patients and invasive activity of breast cancer cells, promoted by an interaction with the cytoskeleton dynamics." (PMID 34639239, 2021). "To test whether the upregulation of S100A14 expression is associated with copy number amplification in breast cancer, we analyzed S100A14 copy number alterations using breast cancer data from The Cancer Genome Atlas (TCGA)." (PMID 32483412, 2020). "TPA stimulates breast cancer cell motility by modulating the expression and activity of S100A14 in a KLF4-dependent manner." (PMID 40182023, 2025). "Results showed that ionizing radiation and estrogen affected the expression of those genes that encoded the S100 calcium-binding proteins such as S100P, S100A14, S100A2, S100A8, and S100A9 in the immortalized breast cancer cell line MCF-10F." (PMID 39594999, 2024). "Colocalization analysis showed that S100A14 (PP.H4.abf = 0.920) and S100A16 (PP.H4.abf = 0.932) shared causal variation with HER-positive breast cancer, and PDE5A (PP.H4.abf = 0.857) shared causal variation with colorectal cancer (CRC)." (PMID 38762700, 2024). "For example, copy number amplification of S100A14, significantly correlated with the increased S100A14 mRNA expression, is present in 5.4 to 20.7% of primary breast cancer patients and in approximately 26.1% of metastatic breast cancer patients." (PMID 36857450, 2023). "S100A14 triggers the MAPK pathway, which causes lung adenocarcinoma, epithelial-mesenchymal transition cervical cancer cells, and metastatic breast cancer cells to proliferate." (PMID 36613714, 2022). "Although the involvement of S100A14 in the translocation from the cytosol to the plasma membrane in breast cancer is well known, S100A14 has also been discovered to play a dynamic role in bladder cancer and growth." (PMID 36613714, 2022). "The same is valid for the S100-A14 protein, which has so far been described as a breast cancer biomarker." (PMID 33546239, 2021). "Consistent with our results, in breast cancer the expression of S100A14 provides poor prognosis in breast cancer patients." (PMID 34824288, 2021). "Overexpression of S100A14 has been found in some kinds of cancers, such as breast cancer, lung cancer and bladder cancer." (PMID 33815482, 2021).
breast carcinoma (continued). "We previously reported that S100A14 enhances breast cancer cell migration and invasion, prompting us to further explore the role of S100A14 in the metastasis of breast cancer in the physiological context." (PMID 32483412, 2020). "S100A14 serum levels were significantly increased in distant breast cancer patients compared with regional breast cancer patients (P = 0.001)." (PMID 32984913, 2020). "The results showed that copy number amplification of S100A14 was present in 5.4%-20.7% of primary breast cancer patients, but S100A14 amplification was found in approximately 26.1% of metastatic breast cancer patients." (PMID 32483412, 2020). "By analyzing the TCGA data, we found that the S100A14 gene is amplified in breast cancer, and the frequency of amplification is higher in metastatic tumors than the primary tumors." (PMID 32483412, 2020). "Collectively, these data demonstrate that S100A14 promotes breast cancer metastasis in an intracellular and extracellular manner." (PMID 32483412, 2020). "Mechanistic studies demonstrated that S100A14 promotes breast cancer metastasis by upregulating the expression and secretion of CCL2 and CXCL5 via NF-κB mediated transcription." (PMID 32483412, 2020). "By analyzing S100A14-regulated transcriptome and proteome in breast cancer cells, we found that S100A14 regulates the expression of a panel of inflammatory chemokines and cytokines." (PMID 32483412, 2020). "A marked increase in S100A14 secretion was found in S100A14-overexpressing breast cancer cells, whereas a striking reduction was observed in S100A14-knockout MCFCA1a cells." (PMID 32483412, 2020). "To uncover the molecular mechanisms by which S100A14 promotes breast cancer metastasis, we performed RNA-Seq and quantitative proteomics analyses of secreted proteins in S100A14-overexpressing 4T1 cells and control cells." (PMID 32483412, 2020). "First, we screened the expression of S100A14 in nine breast cancer cell lines and normal breast epithelial cells by Western blot." (PMID 32483412, 2020). "S100A14 expression was obviously upregulated in breast cancer tissues compared with the matched normal tissues." (PMID 32483412, 2020). "Here, we provide compelling evidence that S100A14 acts as a prominent promoter of breast cancer cell and macrophage migration and invasion." (PMID 32483412, 2020). "Our IHC analysis showed that S100A14 expression is elevated in breast cancer tissues compared with the matched adjacent normal tissues." (PMID 32483412, 2020). "The elevation of S100A14 levels in distant breast cancer patients suggests the ability of using serum S100A14 as a biomarker for detection of breast cancer metastasis." (PMID 32984913, 2020). "Collectively, these results strongly indicate that S100A14 facilitates breast cancer metastasis and drives poor prognosis." (PMID 32483412, 2020). "The orthotopic mammary fat pad transplantation of 4T1 cells further validated that S100A14 enhances breast cancer cell metastasis." (PMID 32483412, 2020). "And the results demonstrated that S100A14 enhanced breast cancer metastasis, but S100A14-promoting metastasis was blocked by TAM depletion with Liposomal Clodronate." (PMID 32483412, 2020). "In summary, our results identify a S100A14- NF-κB -CCL2/CXCL5 signaling axis in promoting breast cancer metastasis." (PMID 32483412, 2020). "In breast cancer tissues and cell lines, S100A14 has been found to co-localize with HER2 and actin proteins." (PMID 31105881, 2019). "It is known that S100 proteins are upregulated in basal‐like breast carcinomas and increased expression of S100A11 and S100A14 was correlated with poor outcome in breast cancer." (PMID 30980596, 2019). "The co-expression of S100A14 and S100A16 was associated with a poor prognosis in human breast cancer as it was reported to promote cancer cell invasion via an interaction with cytoskeletal dynamics." (PMID 31877708, 2019).
breast carcinoma (continued). "S100A14 expression is positively correlated with HER2 expression in breast cancer tissues, and S100A14 can bind to and phosphorylate HER2 in a Ca2+-dependent manner and consequently increase cell growth." (PMID 28051137, 2017). "S100A14 has been studied in breast cancer progression and is showed to be involved in EMT in human cervical and pancreatic cancer cells." (PMID 28651527, 2017). "The overexpression of S100A14 is related with poor prognoses in breast cancer, liver cancer, cervical cancer and ovarian cancer but is associated with favorable outcomes in colorectal and small intestinal cancers." (PMID 27270322, 2016). "It is co-expressed with S100A14 in oral squamous cell cancer, breast cancer, and several cancer cell lines." (PMID 27241529, 2016). "The regulation direction between KLF4 and S100A14 was also demonstrated in breast cancer, as was the inference from our Bayesian network." (PMID 27270322, 2016). "Immunohistochemical analysis of 167 breast cancer cases showed strong cell membrane staining of S100A14 (53% of cases) and S100A16 (31% of cases) with a significant number of cases with co-expression (p < 0.001)." (PMID 25884418, 2015). "This is the first report in which the clinical significance of S100A14 protein expression as an independent prognostic factor in breast cancer has been demonstrated." (PMID 25884418, 2015). "The overexpression of S100A14 was correlated with poorer prognosis in breast cancer and liver cancer, while it was correlated with favorable prognosis in colorectal and small intestinal cancers." (PMID 25884418, 2015). "WalBC cells showed regulated expression of DSP, s100A14 and ANXA1 which are genes associated with well-differentiated, epithelioid breast cancer cell lines with weak invasive potential and poorly invasive tumors." (PMID 18179684, 2008). "Others reported that the S100A14 signaling promoted the metastasis of breast cancer when serum levels were higher in patients with advanced breast cancer in comparison to those with localized one; then, high levels of S100A14 expression were linked to lower survival rates in breast cancer patients." (PMID 39594999, 2024). "The clinical analysis indicated that among them, the S100A14 gene could serve as an effective marker for cancer development at early stages for Lumina A patients and later stages for Her2 breast cancer patients." (PMID 39594999, 2024). "Studies had shown that S100A14 might be related to the breast cancer metastasis by promoting expression of chemokines CCL2 and CXCL546." (PMID 38762700, 2024). "S100A14 is a modulator of HER2 signaling pathway in breast cancer, but this gene might be responsible for development of pituitary prolactinoma." (PMID 33709028, 2021). "Notably, the conditioned medium from S100A14-overexpressing cells significantly enhanced the migration and invasion of breast cancer cells." (PMID 32483412, 2020). "And S100A14 has the potential to serve as a serological marker for diagnosis of breast cancer." (PMID 32483412, 2020). "Notably, the serum levels of S100A14, CCL2/CXCL5 have significant diagnostic value for discerning breast cancer patients from healthy individuals." (PMID 32483412, 2020). "Here, we showed that S100A14 promotes breast cancer metastasis." (PMID 32483412, 2020). "To define the physiological significance of these observations, we first analyzed the expression of S100A14 in 233 paired breast cancer specimens and adjacent normal tissues, 177 cases of lymph node specimens with metastasis and 174 cases of lymph node specimens without metastasis by IHC." (PMID 32483412, 2020). "High S100A14 serum levels were correlated with poor tumor differentiation so it might have a prognostic significance for breast cancer tumors." (PMID 32984913, 2020). "Current studies demonstrated that S100A14 can be secreted into the extracellular space, which prompted us to evaluate whether S100A14 may be a potent serum biomarker in breast cancer." (PMID 32483412, 2020).
breast carcinoma (continued). "However, how S100A14 enhances breast cancer metastasis via exosomal pathway still needs to be further studied." (PMID 32483412, 2020). "Although previous literatures showed that several S100 proteins can be packaged into exosomes to activate PI3K/AKT and NF-κB signaling pathways 38, 39, we for the first time showed that S100A14 in exosomes can be transferred to cancer cells and macrophages and promotes breast cancer metastasis." (PMID 32483412, 2020). "S100A14 has been reported to be upregulated in breast cancers." (PMID 31105881, 2019). "Because of the close correlation between S100A14 and HER2 expression in breast cancer, the prognosis of S100A14-positive patients could be affected by HER2 status when prognosis was analyzed using standard statistical methods." (PMID 25884418, 2015). "To determine the contribution of S100 protein expression to breast cancer, we first used immunohistochemistry to analyze S100A14 and S100A16 protein expression in tissue samples of 167 patients who underwent surgical resection for primary invasive breast cancer." (PMID 25884418, 2015). "S100A14 overexpression is also well established in breast cancer." (PMID 23460839, 2013). "The proteomic comparisons notably led to the identification of five proteins that are used as breast cancer diagnostic and prognostic biomarkers: proliferating cell nuclear antigen (PCNA), cathepsin D, cathepsin B, protein S100-A14, and heat shock protein beta-1 (HSP27)." (PMID 22384035, 2012). "Additionally, clinical data revealed a positive association between ESR1 and S100A14 gene expression in patients with Basal and Her2 breast cancer, but a negative correlation in patients with Luminal A and Luminal B breast cancer." (PMID 39594999, 2024). "Interestingly, a study had shown that co-expression of S100A16 and S100A14 in breast cancer promoted the invasive ability of cancer cells; overexpression and knockdown of S100A14 could affect the expression of S100A1649." (PMID 38762700, 2024). "To further confirm whether CCL2 and CXCL5 function as pivotal chemokines mediating S100A14-induced breast cancer metastasis in vivo, we used the 4T1 orthotopic transplantation model in which mice were treated with CCL2- and CXCL5-neutralizing antibodies or IgG control antibodies." (PMID 32483412, 2020). "Importantly, S100A14 expression is highly associated with CCL2 and CXCL5 expression in breast cancer tissue and serum samples, supporting our hypothesis that S100A14 regulates CCL2/CXCL5 expression in a physiological context." (PMID 32483412, 2020). "Additionally, S100A14 was found to interact with HER2 in breast cancer cells." (PMID 31105881, 2019). "Furthermore, several other studies have supported the role of S100A14 in breast cancer progression." (PMID 31105881, 2019). "Although the function of S100A14 in breast cancer remains to be elucidated, it has been suggested that S100A14 binds HER2 and modulates its phosphorylation, leading to HER2-stimulated cell proliferation, indicating that S100A14 may be a functional partner of HER2 in HER2-positive breast tumors." (PMID 29156846, 2017). "Therefore, we speculated that S100A14 might play a leading role in breast cancer." (PMID 38762700, 2024). "In the present study, we identified S100A14 as a novel upstream regulator of CCL2, administration of CCL2 blocking antibody led to decreased breast cancer metastasis, providing an alternative strategy for targeting the CCL2 signaling pathway." (PMID 32483412, 2020). "Analysis of published datasets found that the coexpression of S100A14 and CCL2/CXCL5 in breast cancer tissues is a significant determinant of poor metastasis-free survival for breast cancer patients." (PMID 32483412, 2020).